TSTD3P (thiosulfate sulfurtransferase like domain containing 3, pseudogene)
Synonyms: TSTD3
Tractability: PROTAC: its protein half-life has been measured.
Gene: Transcribed unitary pseudogene on chromosome 6 (99,520,976 to 99,589,899, forward strand). Ensembl gene ENSG00000279170.
Genetic constraint (gnomAD): Loss-of-function variants: 4 observed, 3.69 expected, observed/expected ratio (o/e) 1.08, 90% interval 0.51 to 1.87. That is too few expected variants to judge how well the gene tolerates losing a copy. Missense variants: 50 observed, 44.44 expected, observed/expected ratio (o/e) 1.13, 90% interval 0.9 to 1.42. Synonymous variants: 20 observed, 13.77 expected, observed/expected ratio (o/e) 1.45, 90% interval 1.01 to 1.9.
Diseases named in the same sentence as TSTD3P in open-access papers:
TSTD3P is named in the same sentence as 1 disease in open-access papers, as found by Europe PMC text mining. Sharing a sentence is not in itself a finding about the gene and the disease.
TSTD3P shares sentences with these, for which no sentence is quoted: melanoma (1 paper).